AQP7P1 (aquaporin 7 pseudogene 1)
Gene: Transcribed unprocessed pseudogene on chromosome 9 (63,317,067 to 63,333,091, reverse strand). Ensembl gene ENSG00000186466.
Diseases named in the same sentence as AQP7P1 in open-access papers:
AQP7P1 is named in the same sentence as 3 diseases in open-access papers, as found by Europe PMC text mining. Sharing a sentence is not in itself a finding about the gene and the disease. The quoted sentences say what the papers report.
COVID-19 (1 paper, 2025). A disease caused by infection with severe acute respiratory syndrome coronavirus 2. "AQP7P1 (FDR = 7.34 × 10−3), PFN1P2 (FDR = 1.61 × 10−2), AL590452.1, and LINC00842 (FDR < 0.05) were significantly associated with COVID-19 BIs." (PMID 40650217, 2025).
AQP7P1 also shares sentences with these, for which no sentence is quoted: cancer (1 paper); tumor (1).